SNORD25 (small nucleolar RNA, C/D box 25)
Synonyms: U25; RNU25
Gene: Small nucleolar RNA gene on chromosome 11 (62,855,564 to 62,855,632, reverse strand). Ensembl gene ENSG00000275043.
Gene Ontology:
Biological process: RNA processing
Cellular component: nucleolus
Homologues: Orthologues: chimpanzee SNORD25 (99% identical), mouse Gm25855 (87% identical).
Diseases named in the same sentence as SNORD25 in open-access papers:
SNORD25 is named in the same sentence as 4 diseases in open-access papers, as found by Europe PMC text mining. Sharing a sentence is not in itself a finding about the gene and the disease. The quoted sentences say what the papers report.
breast carcinoma (1 paper, 2015). "In addition, up-regulation of SNORD28 but not SNORD25 in breast cancer tissues also indicates existence of extensive posttranscriptional regulation." (PMID 26061048, 2015).
infection (1 paper, 2022). The state of being infected such as from the introduction of a foreign agent such as serum, vaccine, antigenic substance or organism. "The silencing of SNORA/Ds encoded within RPS11 (SNORD35B), SNHG3 (SNORA73A, SNORA73B), and SNHG1 (SNORD22, SNORD25, SNORD26, SNORD27, SNORD28, SNORD29, SNORD30, SNORD31) inhibited infection with influenza A virus." (PMID 36430145, 2022).
SNORD25 also shares sentences with these, for which no sentence is quoted: cancer (1 paper); peripheral T-cell Lymphoma (1).